PFKFB3 (6-phosphofructo-2-kinase/fructose-2,6-biphosphatase 3)
Diseases named in the same sentence as PFKFB3 in open-access papers (continued):
Sharing a sentence is not in itself a finding about the gene and the disease.
cancer (continued). "A derivative of the small molecule 3-(3-pyridinyl)-1-(4-pyridinyl)-2-propen-1-one (3PO) exhibited PFKFB3 inhibitory potential with promising anti-cancer effects." (PMID 36984785, 2023). "Since APC/CCDH1 negatively regulates the level of PFKFB3 in cancer cells by ubiquitination, APC/CCDH1 plays a role in inhibiting cancer cell growth." (PMID 37176148, 2023). "Overwhelming evidence substantiates that increased expression or phosphorylation of PFKFB3 facilitates the progression and glycolysis in various cancers." (PMID 36990998, 2023). "We have used the UALCAN database to investigate the promoter methylation level of PFKFB3 in human pan-cancer." (PMID 37253634, 2023). "Specifically, PFKFB3, having the strongest phosphofructo-2-kinase activity, is typically up-regulated in cancers, including HCC." (PMID 36776894, 2023). "PFKFB3 has emerged as a key oncogene in several types of cancer; it plays a considerable role in the regulation of glycolysis in cancer cells and in the proliferation and survival of cancer cells." (PMID 37919747, 2023). "To explore immune cell infiltration of PFKFB3 in cancers, we analyzed the correlation between the immune cell infiltration and PFKFB3 expression in TCGA pan-cancer." (PMID 37253634, 2023). "S461 of PFKFB3 has been demonstrated as a key phosphorylation site for its stimulatory effect on F2,6BP production, lactate secretion, and proliferation in cancer cells." (PMID 36990998, 2023). "The knockdown of PFKFB3 inhibits the expression of cancer stemness markers such as CD133, ALDH1A1, CD44, Sox2, and ABCG2, which are also associated with chemotherapy resistance." (PMID 37919747, 2023). "HO-1 stimulation or CO production results in decreased methylation of PFKFB3 in various cancer cells to repress F-2,6-BP, altering glucose consumption from glycolysis toward the pentose phosphate pathway (PPP)." (PMID 36978983, 2023). "The KEGG pathway results identified that PFKFB3 correlated genes were involved in melanogenesis, proteoglycans in cancer, and pathways in cancer." (PMID 37253634, 2023). "PFKFB3 protein levels are overexpressed in a wide variety of cancers and its expression or activity has been found to be strongly correlated with the aggressiveness and poor prognosis of the cancer." (PMID 35804016, 2022). "PFKFB3 (6-phosphofructo-2-kinase/fructose-2,6-bisphosphatase-3) is a key regulator of high glycolytic flux in cancers by catalyzing the synthesis of F2,6P2 which allosterically activates PFK-1, the rate-limiting enzyme of glycolysis." (PMID 35804016, 2022). "Typically, the cancer-specific isoenzymes PFKFB3 and PFKFB4 keep the F-2,6-BP content in the cytoplasm stable." (PMID 36276846, 2022). "A major PFKFB3 as a cancer-therapeutic target has emerged in rapidly growing cancer cells to regulate metabolic proliferation and several inhibitory agents." (PMID 36077431, 2022). "Since PFKFB3 was previously reported as an important metabolic target in cancer, we focused our current study to unravel its role in cancer stemness, EMT alteration, and therapeutic resistance by effluxing drugs." (PMID 35804016, 2022). "Here, we found that PFKFB3, another key enzyme in promoting glycolysis, was up-regulated in ascites-derived cancer cells." (PMID 35155224, 2022). "PFKFB3 has been reported to be up-regulated in malignant tumors compared with normal tissue in leukemia and several human cancers, including colorectal, breast, lung, thyroid and nasopharyngeal cancer." (PMID 35155224, 2022). "PFKFB3 inhibitor PFK158 has been reported to inhibit the progression of several types of cancer cells at relatively low concentrations." (PMID 35804016, 2022). "PFKFB3 was upregulated in multiple cancers, and PFKFB3 overexpression promoted the proliferation and metastasis of cancer cells." (PMID 35094634, 2022).
cancer (continued). "Other studies have also shown that PFKFB3 was transported to the nucleus in cancer cells, with external-influenced PFKFB3 wild-type expression within the nucleus led to exacerbated cell proliferative activity, without any influences on glycolytic processes." (PMID 35057732, 2022). "In view of its significance in cancer metabolism, it is necessary to further study the function of PFKFB3 in diverse cancers." (PMID 35094634, 2022). "PFK15 has been reported to be a specific and potent small molecule antagonist of PFKFB3, and is able to suppress the proliferation of various cancer cells." (PMID 35209949, 2022). "To determine if PFKFB3 expression impacts the cancer stem cells, we generated stable shRNA mediated PFKFB3 KD clones in H1048 and H1882 cells (sh55PFKFB3and sh59PFKFB3) along with non-targeted control (NTC) shRNA control cells." (PMID 35804016, 2022). "PFKFB3 is overexpressed in various cancers, including breast, colon, nasopharyngeal, pancreatic, and gastric cancers, and is associated with lymph node metastasis and survival." (PMID 36230492, 2022). "In this study, we examined the effects of targeting PFKFB3 with genetic knockdown or with glycolytic inhibitor PFK158 (a specific inhibitor of PFKFB3) on cancer stemness, YAP/TAZ signaling, EMT, and therapeutic resistance for SCLC in vitro and in vivo." (PMID 35804016, 2022). "Isoform PFKFB3, which is highly expressed in most cancers, is inducible by hypoxia and promotes glycolysis under hypoxic conditions." (PMID 36304460, 2022). "Our research team successfully separated and cultured human oral CAFs from human cancer, and verified the upregulated glycolysis via PFKFB3 and PKM2 overexpression in oral CAFs." (PMID 36115986, 2022). "In the cytoplasm, PFKFB3 was found to be more highly expressed in malignant tumors than in normal tissues/benign tumors." (PMID 35155224, 2022). "Inactivation of the glycolytic enzyme PFKFB3 (6-phosphofructo-2-kinase/fructose-2,6-biphosphatase) suppresses glycolysis level and contributes to decreased proliferation and migration of cancer (tumorigenesis) and endothelial (angiogenesis) cells." (PMID 36430773, 2022). "Among the four currently identified PFKFB isoforms (termed PFKFB1 to 4), PFKFB3 is the strongest glycolysis-inducer and is upregulated in many human cancers." (PMID 36217026, 2022). "Then, a mouse CAC model was established to detect the level of PFKFB3, and significantly increased PFKFB3 expression was detected in the inflamed, dysplastic, and carcinoma tissues." (PMID 36016583, 2022). "PFKFB3 stimulates glycolytic flux to support cancer cell growth, and for oncogenic Ras signaling pathway, it is a necessary glycolytic mediator." (PMID 33931981, 2021). "PFKFB3 post-transcriptional regulation by miR-206 and miR-26b has been shown to reduce glycolysis, cell proliferation, and migration in cancer cells by direct interaction with the 3′UTR of PFKFB3 mRNA." (PMID 34831136, 2021). "Overexpression of PFKFB3 in cancer contributes to cyclin-dependent kinases, leading to the phosphorylation and degradation of Cip/Kip protein p27, thereby facilitating the cell cycle, enhancing cell proliferation, and inhibiting apoptosis." (PMID 34540667, 2021). "Excessive blockade of PFKFB3 can, however, facilitate metastasis and cancer cell extravasation by damaging the vascular integrity." (PMID 34831136, 2021). "The intracellular concentration of F2,6P2 in cancers is maintained primarily by PFKFB3 allowing cancer cells to evade glycolytic suppression." (PMID 34831136, 2021). "As a secondary option for cancer cells, PFKFB3 regulation in the setting of elevated ROS levels provides cells with the ability to escape the consequences of oxidative toxicity while continuing to use glucose." (PMID 34831136, 2021). "Increased PFKFB3 is considered a prognostic marker of cancer because it is related to Ki-67 expression, which is a marker of cell proliferation." (PMID 33922320, 2021).
cancer (continued). "Cancer stem cells (CSCs) can be distinguished from induced pluripotent stem cells (iPS) purely by the expression levels of PFKFB3 and PFK-1, as PFKFB3 overexpression is typical of CSCs." (PMID 34831136, 2021). "A majority of cancers rely on the induction of PFKFB3 and the acceleration of the glycolytic flux for enhanced cellular proliferation." (PMID 33898429, 2021). "Studies have supported the role of p27 in the regulation of cell proliferation and apoptosis, and increased levels of this protein were observed in cancer cells after PFKFB3 knock-out." (PMID 33922320, 2021). "Following platin administration, cancer cell viability is significantly reduced when autophagy is inhibited, an effect that can be potentiated by the inhibition of PFKFB3 as this restricts autophagy through interfering with its initiation." (PMID 33671514, 2021). "PFKFB3 is involved in the Ras signaling pathway, which is considered a regulator of glucose metabolism in cancer." (PMID 33671514, 2021). "In cancer research, PFKFB3 has already been extensively studied as a target for therapeutic intervention." (PMID 34084561, 2021). "Activation of the mTOR signaling pathway upregulates PFKFB3 expression, which suggests a close connection between increased glycolytic flux and cancer development." (PMID 33671514, 2021). "Studies have shown the role of PFKFB3 in regulation of glycolysis, proliferation, migration, and angiogenesis of cancer cells." (PMID 33739370, 2021). "Accumulating studies have suggested that PFKFB3 can promote the oncogenesis, proliferation and survival of cancer cells." (PMID 33407885, 2021). "To date, many PFKFB3 inhibitors have been designed, synthesized, and tested in vitro and/or in vivo to evaluate their potential in anti-cancer therapy." (PMID 35056904, 2021). "We further validate PFKFB3-dependent regulation of FA repair in ex vivo cultures from cancer patients." (PMID 34298817, 2021). "Intriguingly, we observed an increase in glycolytic capacity and reserve following TGFβ2 treatment which was accompanied by an increased expression of glycolytic enzymes, PFKFB3, PKM2 and LDHA, linked to EMT in cancer metastasis models." (PMID 33946753, 2021). "AMP-activated protein kinase (AMPK) maintains energy homeostasis, which can positively regulate PFKFB3 to promote glycolysis, thereby increasing glucose uptake for cancer cell proliferation." (PMID 34079757, 2021). "Overall, cancer cells can adapt to stressful conditions and continue to proliferate in part due to the diverse and reversible functions of PFKFB3." (PMID 34831136, 2021). "Inhibition of PFKFB3 displays a cancer-specific synergy with platinum compounds in blocking cell viability and restores sensitivity in treatment-resistant models." (PMID 34298817, 2021). "As endocytosis in endothelial cells requires ATP from glycolysis, inhibition of PFKFB3 promotes high-level expression of VE-cadherin in ECs, which tightens the vascular barrier and reduces the invasion of cancer cells." (PMID 33777937, 2021). "Stabilize PFKFB3 by blocking its ubiquitination and degradation thus promoting glycolysis in cancer cells." (PMID 33868368, 2021). "Heme oxygenase 1 and carbon monoxide can induce PFKFB3 hypomethylation and polyubiquitination to help cancer cells resist oxidative stress." (PMID 33931981, 2021). "Similar results are expected for combined therapy with HER2 and PFKFB3 inhibitors in trastuzumab-resistant cancer." (PMID 33671514, 2021). "In many types of cancer, higher expression of PFKFB3 or PFKFB4 correlates with shorter overall survival (OS) or a more frequent presence of metastases." (PMID 33671514, 2021). "Another isoform of PFKs, namely PFKFB3, which is overexpressed in cancer cells, has been targeted therapeutically using PFK15 (1-(4-pyridinyl)-3-(2-quinolinyl)-2-propen-1-one)." (PMID 33440853, 2021).
cancer (continued). "The enzyme 6-phosphofructo-2-kinase/fructose-2,6,-bisphophatase 3 (PFKFB3) is commonly overexpressed in cancer where it promotes angiogenesis, migration, and proliferation." (PMID 34298817, 2021). "The novel role of PFKFB3 in mediating repair upon ICL-inducing agents presented here brings the opportunity for a combination treatment that is synthetic lethal to cancer cells." (PMID 34298817, 2021). "The intracellular concentration of F2,6P2 in cancers is maintained primarily by the PFKFB3 bifunctional enzyme." (PMID 34831136, 2021). "PFKFB3 is overexpressed in a variety of aggressive human cancers and is one of the primary enzymes responsible for the glycolytic TMR." (PMID 34831136, 2021). "The involvement of PFKFB3 in cancer cell tumorigenic reprogramming is witnessed in various steps of cellular transformation, including metabolic reprogramming, cell cycle regulation, angiogenesis, and DNA repair." (PMID 34831136, 2021). "After that, the role of PFKFB3 in the metabolic control of cancer cell glycolysis has been widely reported 33-35." (PMID 33390824, 2021). "Protein levels of the glycolysis regulator PFKFB3 are overexpressed in a variety of cancers, and expression of this enzyme is strongly correlated with a poor prognosis." (PMID 33922320, 2021). "PFKFB3 (6-phosphofructo-2-kinase/fructose-2,6-biphosphatase 3) expression is increased in cancer and it acts as an allosteric activator of the glycolytic enzyme phosphofructokinase 1 (PFK1), stimulating glycolysis." (PMID 34150624, 2021). "Here, we identify novel regulation of FA repair by the cancer-associated glycolytic enzyme PFKFB3 that has functional consequences for replication-associated ICL repair and cancer cell survival." (PMID 34298817, 2021). "PFKFB3 has a largely detrimental role in supporting cancer cell growth, by promoting glycolysis, cell cycle progression, and angiogenesis." (PMID 34044589, 2021). "Cancer cell intravasation/extravasation is also largely influenced by PFKFB3, as it increases the expression of tumor cell adhesion molecules, VCAM-1, ICAM-1, and E- selectin by NF-κB signaling." (PMID 34831136, 2021). "As such, subcellular PFKFB3 nuclear localization allows cancer cells to continue cellular growth and proliferation even in a nutrient-poor environment." (PMID 34831136, 2021). "Although a few recent studies have provided some data on the role of autophagy following PFKFB3 inhibition treatment in cancer, the relationship between PFKFB3 and autophagy in cancers remains controversial." (PMID 33420377, 2021). "Our results showed that KAN0438757 efficiently targets PFKFB3 expression and was able to affect cancer cell motility, invasion and survival." (PMID 33671096, 2021). "The intracellular concentration of F2,6P2 in cancers is primarily maintained by PFKFB3, allowing cancer cells to evade glycolytic suppression." (PMID 34831136, 2021). "Glycolysis induces NF-KB-driven vascular inflammation through lactate signaling, which is why a PFKFB3 blockade reduces vascular inflammation and related cancer cell metastasis." (PMID 33777937, 2021). "Collectively, targeting PFKFB3 opens up therapeutic possibilities to improve the efficacy of ICL-inducing cancer treatments." (PMID 34298817, 2021). "Our findings are corroborated by other studies, which have also shown that PFKFB3 expression is involved in cancer cell viability and that PFKFB3 inhibition can induce cell death." (PMID 33671096, 2021). "PFKFB3 has been shown to be one of the key factors involved in the glycolytic rewiring found in most cancer cells, including those in the central nervous system (CNS)." (PMID 34831136, 2021).
cancer (continued). "PARP cleavage is a marker of apoptosis and thus the ratio of cleaved: whole PARP was assessed in MIA PaCa-2, BxPC-3 and human pancreatic stellate cells (HPSCs), as a non-cancer control with much lower PFKFB3 expression." (PMID 32266066, 2020). "An enzyme that regulates glycolysis, 6-phosphofructo-2-kinase/fructose-2,6-biphosphatase 3 (PFKFB3), is a target for cancer chemotherapy, for the small-molecule inhibitors of PFKFB3 reduce growth of CRC cells." (PMID 32218208, 2020). "Inhibition of the key glycolytic activator 6-phosphofructokinase 2/fructose-2,6-bisphosphatase-3 (PFKFB3) by 3-(3-pyridinyl)-1-(4-pyridinyl)-2-propen-1-one (3PO) strongly attenuates pathological angiogenesis in cancer and inflammation." (PMID 32130250, 2020). "Collectively, these results suggest that AGPG and PFKFB3 are closely related and that their interaction plays an important role in human cancer development." (PMID 32198345, 2020). "This metabolic switch was at least in part driven by expression of PFKFB3, a recognized mediator of heightened glucose fermentation in cancer cells." (PMID 32841216, 2020). "By preventing APC/C-mediated ubiquitination, AGPG protects PFKFB3 from proteasomal degradation, leading to the accumulation of PFKFB3 in cancer cells, which subsequently activates glycolytic flux and promotes cell cycle progression." (PMID 32198345, 2020). "PFKFB3 has been considered a promising therapeutic target in cancer, primarily because of its role in supporting the high glycolytic rates required to fuel rapid cellular proliferation." (PMID 32130250, 2020). "PFKFB3 is overexpressed in numerous cancers including PDAC; this finding led to the development of the specific small-molecule inhibitor 3PO and then more potent 3PO derivatives: PFK15 and PFK158." (PMID 32266066, 2020). "As reported, PFKFB3 inhibition is a promising modality for cancer treatment because it suppresses glycolysis, proliferation, and metastasis in cancer cells." (PMID 32198345, 2020). "To confirm the role of PFKFB3-S172 phosphorylation in cancer cell proliferation, we depleted endogenous PFKFB3 in SW1990 cells, and reconstituted the expression of RNAi-resistant rPFKFB3 and rPFKFB3 S172A." (PMID 32060258, 2020). "PFKFB3 encodes the isoforms present in the brain, placenta, and adipose tissues, and is the most abundantly expressed PFKFB gene in proliferation and cancer cells." (PMID 32717953, 2020). "PFKFB3 has a critical influence on various stages of cancer progression, such as proliferation, drug resistance, angiogenesis, etc.." (PMID 32806533, 2020). "Inhibitors of PFKFB3 can target specific cell types such as cancer cells, cancer stem cells, endothelial cells, and immune cells." (PMID 32806533, 2020). "Among them, PFKFB3 is the most frequently overexpressed in various human cancers and has been reported to promote proliferation and carcinogenesis." (PMID 31627130, 2019). "Nevertheless, up to this day, most research on PFK-II refers to one of the two cancer specific isoenzymes PFKFB3 or PFKFB4, undoubtedly neglecting the importance of co-expression of individual isoenzymes." (PMID 31754349, 2019). "PFKFB3, which is highly expressed in cancer cells and rapid proliferating cells, has been reported to play essential roles in regulating metabolism, angiogenesis, as well as inflammation." (PMID 31671668, 2019). "The results of the analysis indicates the importance of PFKFB3/4 co-expression for the clinical outcome of cancer patients." (PMID 31754349, 2019). "In cancer cells, several PFKFB3 inhibitors of different chemical classes have been reported to inhibit glycolysis, on which these cells rely for proliferation and survival." (PMID 31406177, 2019).